RNU6-1059P (RNA, U6 small nuclear 1059, pseudogene)
Gene: Small nuclear RNA gene on chromosome 4 (95,868,667 to 95,868,764, reverse strand). Ensembl gene ENSG00000200622.
Homologues: Orthologues: chimpanzee U6 (100% identical), macaque U6 (83% identical), rat LOC120097661 (67% identical), mouse Gm26181 (65% identical). Paralogues in human: RNU6-207P (82% identical), RNU6-266P (82% identical), RNU6-641P (82% identical), RNU6-1011P (81% identical), RNU6-1145P (81% identical), RNU6-116P (81% identical), RNU6-1181P (81% identical), RNU6-1316P (81% identical), RNU6-188P (81% identical), RNU6-224P (81% identical), RNU6-345P (81% identical), RNU6-38P (81% identical), and 1284 more.